GAS5 (growth arrest specific 5)
Diseases named in the same sentence as GAS5 in open-access papers (continued):
Sharing a sentence is not in itself a finding about the gene and the disease.
cervical carcinoma (52 papers, 2016 to 2025). A carcinoma arising from either the exocervical squamous epithelium or the endocervical glandular epithelium. "Low expression of GAS5 has been demonstrated to be one of the major determinants of chemotherapy resistance, especially in cervical cancer, where low GAS5 expression is associated with poor survival and resistance to cisplatin." (PMID 39958058, 2025). "The low expression of GAS5 was detected in cervical cancer patients, which was associated with high expression of miR-21." (PMID 36438563, 2022). "Conclusively, GAS5 polymorphism rs145204276 is probably applicable to predict 5 years survival HR of cervical cancer patients." (PMID 32547314, 2020). "For example, it was previously found that decreased expression of GAS5 is associated with poor prognosis of cervical cancer patients as well as is tumor suppressive in other types of cancer such as breast cancer and prostate cancer." (PMID 30842470, 2019). "Therefore, we designed this study to explore the relationships of GAS5 genetic variants with the development of cervical cancer and patient survival." (PMID 32547314, 2020). "However, there is a paucity of knowledge regarding the impact of GAS5 genetic variants on cervical cancer patient survival in Taiwan." (PMID 32547314, 2020). "Similarly, GAS5 deficiency by siGAS5 also reduced miR-21 target protein PDCD4 expression in cervical cancer cells." (PMID 31620370, 2019). "GAS5 is downregulated in cervical cancer tissues and cell lines and inhibits cell proliferation and invasion by regulating the expression of target genes such as MMP2 and MMP9 and impacts the STAT-3 pathway." (PMID 39912983, 2025). "GAS5 lncRNA is downregulated in cervical cancer and thereby induces apoptosis, prevent invasion, promote chemo-sensitivity to cisplatin, downregulate PI3K/AKT signalling via miR-21 and PTEN route." (PMID 39912983, 2025). "Another study revealed that YTHDF2 inhibited lncRNA GAS5 in cervical cancer cells by promoting its degradation." (PMID 36816363, 2023). "The experimental results showed that GAS5 enhanced the sensitivity of cervical cancer cells to radiotherapy by inhibiting miR-106b and upregulating IER3." (PMID 35692795, 2022). "It has been reported that lncRNA GAS5 decreased radioresistance through miR-106b/IER3 in cervical cancer." (PMID 35600868, 2022). "LncRNA GAS5 overexpression repressed proliferation, invasion and migration of cervical cancer cells in vitro and in vivo." (PMID 36438563, 2022). "LncRNA GAS5 has been verified to work as a tumor suppressor to control cisplatin resistance via targeting miR-21 in cervical cancer." (PMID 36438563, 2022). "Being a tumor suppressor, GAS-5 is downregulated both in cervical cancer cell lines and cervical cancer tissue." (PMID 35895593, 2022). "Recent studies have shown that GAS5 is positively correlated with radiotherapy sensitivity in cervical cancer." (PMID 35692795, 2022). "Further, it was described that the lncRNA GAS5, which was previously reported to influence radiosensitivity of head and neck cancer, also participates in the radiosensitivity of cervical cancer cell lines by down-regulating miR-106b." (PMID 33803151, 2021). "In the meantime, cervical cancer patients with TC/CC had 5 years survival rate 0.81 (95% CI=0.69-0.92), in comparison with those having TT 0.81 (95% CI=0.70-0.92) in GAS5 rs55829688." (PMID 32547314, 2020). "On the other hand, reduced levels of the lncRNA growth arrest specific 5 (GAS5) in human cervical cancer dictate the up-regulation of miR-205 and its oncogenic role in promoting the proliferation and migration of cervical cells." (PMID 33191398, 2020). "A study using the log-rank test showed that cervical cancer patients with a low Gas5 expression tended to have a shorter overall survival time compared to those with a high Gas5 expression." (PMID 29308053, 2018).
cervical carcinoma (continued). "Furthermore, the tumor-suppressing function of GAS5 was reported in esophageal squamous cell carcinoma, in cervical cancer through the miR-196a/miR-205/FOXO1 axis, and in ovarian cancer via the miR-196a/Homeobox 5 (HOXA5) axis." (PMID 39941145, 2025). "GAS5 sponges miR-21 to enhance the sensitivity of DDP treatment for cervical cancer." (PMID 37993867, 2023). "Several lncRNAs, including HOTAIR, H19, mucosa-associated lymphoid tissue 1 (i.e., MALT1), growth arrest-specific 5 (i.e., GAS5), cervical carcinoma high expressed 1 (i.e., CCHE1), and Pvt1 oncogene (i.e., PVT1), are crucial in tumorigenesis, invasion, metastasis, and radio-resistance." (PMID 37081411, 2023). "Studies have shown that the expression levels of GAS5 is positively correlated with the apoptosis of cervical cancer cells and the sensitivity of chemotherapy drugs, and negatively correlated with the proliferation and metastasis of cervical cancer cells." (PMID 35692795, 2022). "LncRNA GAS5 inhibited the expression of miR-21 in cervical cancer cells." (PMID 36438563, 2022). "HOTAIR, GAS5, TUSC8, and lncRNA-LET may be valuable biomarkers for predicting cervical cancer prognosis, as they are associated with invasion and metastasis." (PMID 36144454, 2022). "Indeed, when overexpressed, GAS5 enhanced the sensitivity of cervical cancer cells to treatment by up-regulating IER3 through mir-106b, proving the existence of an axis of GAS5-miR-106b-IER3 regulating radio-resistance in cancer cells." (PMID 33803151, 2021). "As we know, no study reported the association of GAS5 genetic variants with clinicopathological factors of cervical cancer in Taiwan." (PMID 32547314, 2020). "Moreover, inhibition of GAS5 in cervical cancer cells has shown to increase the proliferation, migration and invasion confirming its oncosuppressor activity in the cervical cancer progression." (PMID 32154165, 2020). "Cervical cancer patients with Ins/Del and Del/Del presented 5 years survival rate 0.79 (95% CI=0.68-0.89), as compared to those with Ins/Ins 0.86 (95% CI=0.76-0.97) in GAS5 rs145204276." (PMID 32547314, 2020). "The tumor-suppressor LncRNA GAS5 was down-regulated in cervical cancer tissues, significantly correlated to advanced cancer progression, and identified as a biomarker for forecasting the clinical states of patients in cervical cancer." (PMID 29720427, 2018). "Furthermore, in cervical cancer, GAS5 acts as a growth and metastasis inhibitor by directly binding and downregulating miR-196a and miR-205, crucial for the proliferation, invasion, and apoptosis of cervical cancer cells." (PMID 40242248, 2025). "Also, GAS5 expression is negatively correlated with the malignancy of cervical cancer, and its overexpression has been shown to reduce cell viability and increase apoptosis in cervical cancer cells." (PMID 37506155, 2023). "In the same work, the authors showed that the inhibition of GAS5 using siRNA determined (i) the decrease in the invasion ability of BC cells, and (ii) inhibition of E-cadherin, as well as the up-regulation of N-cadherin and Vimentin in cervical cancer cells (SiHa cells)." (PMID 37444428, 2023). "Hence, lncRNA GAS5 might be a potential target for reversing cisplatin resistance in cervical cancer." (PMID 36438563, 2022). "Similarly, few reports are available on the connection of GAS5 and miRNAs in cervical cancer." (PMID 33076450, 2020). "GAS5 has been identified as a robust tumor suppressor in several genitourinary cancers, including ovarian, RCC, bladder, prostate, and cervical cancers." (PMID 40242248, 2025). "In cervical cancer, YTHDF2-mediated degradation of the tumor suppressor GAS5 enhances growth and metastasis, and inversely, the lncRNA GAS5-AS1 has the opposite effects." (PMID 37369946, 2023). "Mechanistically, GAS5 inhibited miR-21 expression and elevated the expression of PTEN and influenced the pAkt in cervical cancer cells, leading to suppression of cisplatin resistance." (PMID 36438563, 2022).
cervical carcinoma (continued). "For instance, the lncRNA growth arrest-specific 5 (GAS5) can promote the expression of programmed cell death 4 (PDCD4) by sponging miR-21 and thereby enhance the CDDP sensitivity of cervical cancer cells." (PMID 34893064, 2021). "Many lncRNAs have been shown to participate in the occurrence and progression of cervical cancer, either promoting (like SNHG7) or inhibiting (like GAS5) the disease." (PMID 33328990, 2020). "Also several lncRNAs, comprising among others HOTAIR, MALAT1, GAS5, and MEG3, have shown to be associated with various pathogenic processes such as tumor progression, invasion as well as therapeutic resistance and emerged as new diagnostic and prognostic biomarkers in cervical cancer." (PMID 32154165, 2020). "It is worth to note that several lncRNAs, such as GAS5 and HOTAIR show clinical values for the diagnosis and prognosis of cervical cancers." (PMID 29760583, 2018). "Cao and colleagues demonstrated that decreased GAS5 expression was negatively correlated with the FIGO (International Federation of Gynecology and Obstetrics) stage, vascular invasion, and lymph node metastasis in cervical cancer." (PMID 35736636, 2022). "Moreover, cervical cancer patients with Ins (insertion, AGGCA)/Del and Del/Del (-/-) in GAS5 rs55829688 tended to have poorer hazard ratio (HR) of 5 years survival." (PMID 32547314, 2020).
atherosclerosis (47 papers, 2017 to 2025). A disease characterized by the build-up of fatty material and calcium deposition in the arterial wall resulting in partial or complete occlusion of the arterial lumen. "A single nucleotide polymorphism (SNP), rs145204276, in the GAS5 promoter region is related to the risk of atherosclerosis." (PMID 40563948, 2025). "Harnessing the regulatory capacity of lncRNA GAS5 can potentially foster improved diagnostic methodologies and therapeutic strategies for atherosclerosis." (PMID 40563948, 2025). "Regarding the role of lnc‐GAS5 in the risk of cardio‐cerebrovascular disease, a previous study showed that lnc‐GAS5 was obviously elevated in the plaques of atherosclerosis patients when compared to the levels in healthy populations." (PMID 34921461, 2022). "It should be noted that polymorphism in the GAS5 promoter region, rs145204276 DEL/DEL, which upregulates GAS5 transcription activity, was shown to decrease atherosclerosis risk in a Chinese population." (PMID 34940525, 2021). "SNPs in GAS5 rs145204276 Ins/Del and Del/Del genotypes were associated with a reduced risk of atherosclerosis, because they inhibit cell proliferation and stimulate the apoptosis of endothelial cells by targeting the GAS5/miR-21/PDCD4 signaling pathway." (PMID 32354045, 2020). "For example, Shen and She (2018) reported rs145204276 in the promoter region of GAS5 was associated with the risk of atherosclerosis." (PMID 30873207, 2019). "The phenotypic switching of VSMCs represents a hallmark pathological alteration in atherosclerosis, with emerging evidence suggesting the lncRNA GAS5 may regulate this process." (PMID 40563948, 2025). "lncRNA GAS5 was found to be implicated in several mechanisms associated with atherosclerosis." (PMID 39272765, 2024). "Ultimately, achieving a comprehensive understanding of lncRNA GAS5 in atherosclerosis holds substantial promise for enhancing patient outcomes." (PMID 40563948, 2025). "Exosomal GAS5 is additionally capable of modulating programmed cell death in macrophages and endothelial cells pertinent to atherosclerosis." (PMID 40563948, 2025). "This role of GAS5 in atherosclerosis progression is further supported by a study investigating the role of GAS5 in coronary AS through the miR-194-3p/Thioredoxin-interacting protein (TXNIP) axis." (PMID 39941145, 2025). "Because aberrant lncRNA GAS5 expression correlates with atherosclerosis pathogenesis, it represents a noteworthy candidate biomarker for both diagnostic and prognostic purposes." (PMID 40563948, 2025). "In summary, lncRNA GAS5 exerts multifaceted and critical functions in atherosclerosis onset and progression." (PMID 40563948, 2025). "Overall, GAS5 expression levels correlate with atherosclerosis and its related clinical indicators, both in plaque tissue and circulating blood." (PMID 40563948, 2025). "In conclusion, lncRNA GAS5 is a critical regulatory node in atherosclerosis pathobiology, offering significant opportunities for novel diagnostic and therapeutic interventions." (PMID 40563948, 2025). "Mechanistically, GAS5 modulates atherosclerosis-relevant cellular processes—such as endothelial dysfunction, macrophage polarization, foam cell formation, phenotypic switching of VSMCs, and lipid metabolism—through context-dependent regulatory effects." (PMID 40563948, 2025). "In a recent study, THP-1 macrophages treated with oxidized low-density lipoprotein (ox-LDL) and apolipoprotein E (apoE)−/− mice on a high-fat diet (HFD) were used as vitro and in vivo models, respectively, to investigate the role of GAS5 in atherosclerosis." (PMID 39941145, 2025). "Taken together, lncRNA GAS5 emerges as a critical modulator of macrophage activity in the context of atherosclerosis, impacting inflammatory responses, MMPs regulation, lipid handling, cell survival, foam cell development." (PMID 40563948, 2025).
atherosclerosis (continued). "Nevertheless, the precise roles and operational pathways of GAS5 concerning atherosclerosis remain to be thoroughly clarified." (PMID 40563948, 2025). "This review synthesizes current knowledge on lncRNA Growth Arrest-Specific 5 (GAS5) in atherosclerosis, covering its expression, multifaceted roles in vascular cells, and molecular mechanisms." (PMID 40563948, 2025). "Another long non-coding RNA, growth-arrest-specific 5 (GAS5), which is located on human chromosome 1q25.1, plays a key role in the development of atherosclerosis." (PMID 39273193, 2024). "lncRNA growth arrest-specific 5 (GAS5) is another molecule that is suggested to be involved in the progression of atherosclerosis." (PMID 39272765, 2024). "Recently, lncRNA GAS5 (growth arrest-specific 5) has received attention as a potential biomarker for atherosclerosis." (PMID 35328769, 2022). "For example, exosomes secreted by ox-LDL-stimulated THP-1 monocyte ferryinglncRNA LIPCAR, miR-106a-3p, and GAS5 are reported to promote atherosclerosis byaltering the phenotypes of ECs and VSMCs." (PMID 39077721, 2022). "In contrast to its protective role in VSMCs in the context of ISR, the overexpression of GAS5 facilitates M1 macrophage polarisation and promotes inflammation in diabetes, atherosclerosis and cancer." (PMID 36671717, 2022). "Exogenous lncRNA GAS5 can regulate apoptosis in macrophages and endothelial cells in atherosclerosis." (PMID 36034211, 2022). "For instance, GAS5 has been found highly expressed in atherosclerosis and promotes arterial inflammation." (PMID 33645622, 2021). "Knockdown of GAS5 promotes reverse‐transportation of cholesterol and inhibits intracellular lipid accumulation, ultimately preventing atherosclerosis progression." (PMID 33340430, 2021). "LncRNA growth arrest-specific 5 (GAS5), located on human chromosome 1q25.1, plays a crucial role in atherosclerosis's pathogenesis." (PMID 34179148, 2021). "The role of lncRNA GAS5 in atherogenesis to regulate the apoptosis of macrophages and endothelial cells through exosomes suggests that inhibition of lncRNA GAS5 can be an effective way to treat atherosclerosis." (PMID 33511207, 2021). "Considering lncRNA GAS5 as a target for the treatment of atherosclerosis in humans, it can be seen that GAS5 has proatherogenic properties, promoting methylation of the ABCA1 promoter region." (PMID 34940525, 2021). "The importance of another exosomal lncRNA (GAS5) in atherosclerosis progression has recently been provided by Chen and colleagues, demonstrating that exosomes carrying lncRNA GAS5 enhanced apoptosis in vascular endothelial cells." (PMID 33198302, 2020). "LncRNA GAS5 was highly expressed in the plaques of atherosclerosis collected from patients and animal models." (PMID 33192490, 2020). "Other important experimental data is that LncRNA GAS5 expression seems to be involved in vasculopathy-related processes, thus representing a target for atherosclerosis-related treatments." (PMID 32624686, 2020). "Both human and animal models show higher levels of lncRNA GAS5 in plaques of atherosclerosis compared to healthy vessels." (PMID 32624686, 2020). "LncRNA GAS5 was significantly increased in the plaque of atherosclerosis patients compared to normal people." (PMID 32241300, 2020). "Recently, a few lncRNAs, such as GAS5, NEAT1 and MALAT1 were reported to be associated with regulating atherosclerosis progression and prognosis." (PMID 30873207, 2019). "GAS5 is an lncRNA that has been found to be increased in atherosclerosis and its silencing reduces the apoptosis of macrophages and ECs after treatment with oxidized low density lipoproteins (ox-LDL)." (PMID 31238513, 2019). "Here, the initial aim of this study was to investigate the function of lncRNA GAS5 in atherosclerosis progression." (PMID 28945793, 2017).